RNU6-242P (RNA, U6 small nuclear 242, pseudogene)
Gene: Small nuclear RNA gene on chromosome 2 (43,091,388 to 43,091,494, reverse strand). Ensembl gene ENSG00000207087.
Homologues: Orthologues: chimpanzee U6 (100% identical), macaque U6 (96% identical), guinea pig U6 (91% identical), guinea pig U6 (87% identical), pig U6 (86% identical), dog U6 (85% identical). Paralogues in human: RNU6-41P (91% identical), RNU6-1175P (90% identical), RNU6-11P (90% identical), RNU6-1274P (90% identical), RNU6-37P (90% identical), RNU6-43P (90% identical), RNU6-1011P (89% identical), RNU6-12P (89% identical), RNU6-1331P (89% identical), RNU6-13P (89% identical), RNU6-166P (89% identical), RNU6-189P (89% identical), and 1290 more.